FOLR2 (folate receptor beta)
Diseases named in the same sentence as FOLR2 in open-access papers (continued):
Sharing a sentence is not in itself a finding about the gene and the disease.
tumor (continued). "In conclusion, our results suggest a nexus between malignant/HPC-like cells, onco-fetal PLVAP+ ECs, and FOLR2+ TAMs in the immunosuppressive tumor ecosystem." (PMID 36238304, 2022). "By flow cytometry, the ratio of FOLR2 to TREM2 macrophages was reduced during tumor progression in primary tumors and metastatic lymph nodes." (PMID 35746551, 2022). "The overexpression of PSMB6, HSPA9, DUT, CDK7, and PLK1 was seen in resected tumor tissues compared with adjacent normal tissues, while FOLR2 was expressed more in normal tissues." (PMID 34721732, 2021). "Altogether, these results established a link between the FOLR2 gene and the expression of the PU.1-encoding SPI1 gene in tumor-associated macrophages." (PMID 32532019, 2020). "Recent studies have shown that FOLR2-expressing macrophages comprise a specific subset among the total population of tumor infiltrating macrophages." (PMID 25971554, 2015). "Despite its design to target FRα, OTL38 cross-reacts with folate receptor beta (FRβ), which is predominantly expressed in immune cells, such as tumor-associated macrophages, rather than in the cancerous epithelium." (PMID 39941778, 2025). "These are tissue-resident, rather than tumour-associated, C1Q+ macrophages because state #45 cells significantly more highly express FOLR2, rather than TREM2, relative to state #40." (PMID 39748128, 2025). "For instance, chimeric antigen receptor (CAR)-T cells engineered to recognise folate receptor beta (FRβ), a marker enriched on immunosuppressive TAMs, successfully deplete this population, promote pro-inflammatory polarisation, and suppress tumour growth in preclinical models." (PMID 40948757, 2025). "Interestingly, an increase in CD8+ T cell frequency was observed in tumor samples displaying high global levels of FOLR2 and intratumoral FOLR2 macrophages accompanied by higher levels of PD-1+." (PMID 38972873, 2024). "Notably, targeting FOLR2 with a monoclonal antibody reduced tumor growth in a humanized mouse model of acute myeloid leukemia, coupled with NK cell transfer." (PMID 38426622, 2024). "miR-622 specifically targets and downregulates FOLR2, which could in turn attenuated miR-622-induced tumor growth, suggesting a novel mechanism and treatment target in CRC epigenetic regulation." (PMID 38166756, 2024). "miR-622 regulation on cell cycle and tumor proliferation was discovered, and FOLR2 was screened as functional target of miR-622 using bioinformatics analysis, which was validated via dual luciferase assay and gain-of-function and loss-of-function experiments both in vitro and in vivo." (PMID 38166756, 2024). "FOLR2+ macrophages were predominantly localized in the tumor stroma." (PMID 39702278, 2024). "Interestingly, further scRNA-seq from the sorted myeloid components of the tumor identified expression of Trem2, Cadm1, Folr2, and Mrc1, supporting that both TRM and recruited macrophage build the TAM pool." (PMID 39104525, 2024). "Moreover, the FOLR2+ TRMs are shown to promote T-cell infiltration in the tumor, thereby increasing immunogenicity and antitumor activity." (PMID 39104525, 2024). "CD8+ MAIT cells recruit a good subset of macrophages (FOLR2+) to infiltrate into the tumor microenvironment but are transformed to low‐phagocytosis SPP1+ subsets due to the oxygen competition with proliferating tumor cells nearby." (PMID 39716897, 2024). "Additionally, it has been observed that the occurrence of these FOLR2+ macrophages is found to be associated with an increased prevalence of CD8+ T cells, suggesting an anti-tumor immunological function." (PMID 39170612, 2024). "For example, FOLR2 is preferentially expressed by macrophages with anti-inflammatory properties and FOLR2+ TAMs inhibit both cytokine secretion and the proliferation of tumor-specific T cells." (PMID 36938978, 2023).
tumor (continued). "Interestingly, in tumor tissues, FOLR2+ TAMs are derived from both embryonic and adult bone marrow precursors, demonstrating the ability for adult macrophages to be reprogrammed into a fetal-like state, regardless of ontogeny." (PMID 36938978, 2023). "According to in silico analysis of microarray data, altered mRNA levels of several DNA methylation-related enzymes were detected in tumours vs. healthy biopsies, namely one-carbon metabolism-related genes—which met our analysing criteria—showed upregulation, while FOLR2 was downregulated." (PMID 35655145, 2022). "They utilize markers like CD204, CD206, or folate receptor beta that are not very specific for tumor associated macrophages and even more so not for specific type of tumor." (PMID 27807511, 2016). "Folate uptake is largely mediated by folate receptor(FR)β,encoded by FOLR2 gene, in myeloid immune cells such as granulocytes,monocytes, and especially in macrophages that constitute the reticuloendothelialsystem (RES) and infiltrate the tumor microenvironment." (PMID 39105761, 2024). "Similarly, we find that FOLR2 expression is not specific to tumor-associated hepatic macs but is expressed by KCs in the healthy mouse and human liver." (PMID 35021063, 2022). "Interestingly, FOLR2, CD163, LILRB5, CD209 and C1QC were identified as genes of the “anti-inflammatory gene set”, whose expression is also seen in tissue-resident macrophages and tumor-associated macrophages." (PMID 32532019, 2020). "Compared with Mph_04_SPP1, Mph_03_DAB2 exhibiting higher levels of FOLR2, SLC40A1, and IGF1, which are genes specifically expressed by some reported TAMs that known to play a role in promoting tumor progression 57-59." (PMID 39239526, 2024). "Consistent with the scRNA-seq results, FOLR2 expression was also positively correlated with TRM-related genes (CD163, MRC1, CD163L1 and LYVE1) in the whole-tumor transcriptome from the TCGA STAD database." (PMID 39702278, 2024). "We obtained whole-tumor transcriptomics data from the GSE78523 dataset and observed that the FOLR2 mRNA level was positively correlated with the CD8A mRNA level." (PMID 39702278, 2024). "Research indicates that SELENOP+ Mac can promote anti-tumor immunity by highly expressing FOLR2, IL32, CD3D, and LTC4S and are therefore considered to have anti-tumor effects." (PMID 38755647, 2024). "FOLR2+ TAM1 displayed immunosuppressive interactions with Tregs, supporting the onco-fetal reprogramming of tumor microenvironment (TME) in HCC." (PMID 38229178, 2024). "In our study, four macrophage subsets were identified in primary tumor and metastatic specimens: SPP1+ macrophages, C1QC+ macrophages, CXCL10+ macrophages and FOLR2+ macrophages." (PMID 38519500, 2024). "FOLR2+LYVE1+ Mo-Mp correlates with the remission of RA, which is in line with its known role in pro-tumor immunology via inducing immunosuppression." (PMID 38601143, 2024). "FOLR2+ macrophages, which are located in the perivascular spaces in the tumor tissue, can effectively activate the CD8+ T cells in the tumor nest, and then improve the prognosis of breast cancer patients." (PMID 36845095, 2023). "A recent study demonstrated that FOLR2+ macrophages positively correlated with CD8+ T cell infiltration, suggesting that the RTM_4 cluster exerted an anti-tumor activity in BC." (PMID 36428599, 2022). "Histological analysis showed that FOLR2+ macrophages were primarily localized in the tumor stroma, while TREM2+ TAMs were found both in the stroma and in tumor nests, especially along the invasive margin and forming cell clusters." (PMID 35746551, 2022). "FOLR2+ macrophages have been demonstrated to promote CD8+ T cell infiltration, which suggests that the RTM_4 cluster exerted an anti-tumor activity in BC." (PMID 36428599, 2022). "Given that the APP‒TNFRSF21 axis mediates tumor cell-induced endothelial necroptosis, we inferred that APP+ epithelial cells might induce necroptosis of FOLR2+ macrophages via the APP‒TNFRSF21 axis." (PMID 39702278, 2024).
tumor (continued). "The “Detox-iCAF-enriched immuno-protective ECT4” highlighted the spatial co-occurrence of Detox-iCAF, ap-EC, Mo-DC, and FOLR2+ TAM, characterized by their localization in the peritumoral zone but also within the tumor bed, forming an intra-tumoral peritumor-like stroma." (PMID 38561380, 2024). "We also found from the GEO database that similar experiments have been conducted, where co‐culturing tumor cells alone with monocyte‐derived macrophages (MDM, the initial state of macrophage, like FOLR2+ macrophage in our study) does not promote tumor growth." (PMID 39716897, 2024). "Among nonmalignant cell types, RSPO1+ fibroblasts and FOLR2+ macrophages were identified as potential tumor-suppressing populations and POSTN+ fibroblasts and SPP1+ macrophages were identified as tumor-promoting populations." (PMID 38519500, 2024). "Researchers have also found that an immunosuppressive subset of tumor cells can be distinguished from the nonimmunosuppressive population by its upregulation of folate receptor beta (FRβ) and restriction to immunosuppressive tumor microenvironment." (PMID 37147729, 2023). "For these reasons, we postulate that interactions between FOLR2+ TAMs co-localized with Tregs, fetal-like ECs, and ALB+ tumor epithelial cells could be impacted by anti-angiogenic therapies, thereby, potentially impacting immunotherapy response." (PMID 36938978, 2023). "Stimulation of Tregs by these fetal-like FOLR2+ TAMs is anticipated to be abrogated by anti-CTLA4 therapy, with CD86 instead able act as co-stimulation for the activation of naïve T cells and a subsequently enhanced anti-tumor response." (PMID 36938978, 2023). "Specific targeting of VEGF+ TAM subsets responsible for immunosuppressive angiogenesis, while sparing the T cell attractant FOLR2+ and peri-HEV TAMs, may improve the TME and sensitize the tumor to ICB treatment." (PMID 37251409, 2023). "Buggattie and colleagues presented two distinct macrophage subsets co-expressed with FOLR2 and TIM4, which may have opposing roles in tumorigenesis and tumor immunity across several cancer types." (PMID 37532692, 2023). "Compared with malignant and non-malignant regions, Macro-SPP1 was significantly enriched in the tumor boundary, while Macro-FOLR2 tended to be enriched in non-malignant region and Mono/DC cells tended to be enriched in the region surrounding the TLS." (PMID 36806082, 2023). "TAMs were present in both tumor and metastatic lymph nodes and were defined based on the shared expression of APOE, APOC1, and C1QA-C, and the mutually exclusive expression of TREM2/CADM1 and FOLR2." (PMID 35746551, 2022). "More importantly, FOLR2+ TAMs significantly expressed typical immunosuppressive genes including TGFB1, TGBR1, IL10, and IL10RB, validating the immunosuppressive role of FOLR2+ TAMs in the HCC tumor niche." (PMID 36238304, 2022). "Indeed, FOLR2 expression parallels that of CD163 in tissue-resident macrophages, TAM from various tumor types and inflamed synovium." (PMID 32532019, 2020). "To determine whether the macrophage-restricted expression of FRβ also applies to pathological settings, we next assessed FOLR2 expression in TAM from various tumor types." (PMID 32532019, 2020). "These MØs express CD163 and M2-specific markers (increased expression of FOLR2 and MAF and reduced expression of ActA), and show an upregulated expression of different factors that favour tumour progression (including, among others, IL-10, TGF-β, IL-6, IL-8, IDO1, COX2 and GAL-1)." (PMID 31337120, 2019). "On theother hand, Folr2 was highly and exclusively expressed in the tumorsbut not in the cultured 4T1 cell line which indicated the presenceof FRβ in the cells infiltrating the tumor microenvironment." (PMID 39105761, 2024). "The transition from FOLR2+ macrophages to SPP1+ subsets may represent an adaptation to the microenvironmental stressors, such as hypoxia, which is prevalent in the leading‐edge area due to the high proliferative rate of tumor cells." (PMID 39716897, 2024).
tumor (continued). "Importantly, FOLR2+ HBCs/macrophages, as well as some tumor cells, are the main source of VEGF in tissue ecosystems, thus contributing toward angiogenesis in fetal and tumor development, such as in HCC." (PMID 36938978, 2023). "Importantly, FOLR2 mRNA was strongly expressed by certain stromal cells surrounding the tumor cells of fallopian adenocarcinoma samples but not the tumor cells themselves." (PMID 25971554, 2015). "Given that in clinical practice, although both occurred in the liver, we have clearly found that HCC has an out better blood supply than ICC, it is speculated that FOLR2+ TAM lacks this oxygen competition phenomenon with HCC tumor cells, without the phenotype transformation to SPP1+ macrophages." (PMID 39716897, 2024). "Indeed, when PDAC monocytes interact with tumour-specific CD4+ T cells they can acquire an anti-tumourigenic MHCIIHi phenotype, while in the absence of direct lymphocyte contact, tumour-infiltrated monocytes follow the default differentiation into FOLR2+ TAMs, promoting tumour growth." (PMID 39430099, 2024). "Pronounced tumor-supporting activity of TAMs was also found in a murine model of pancreatic ductal adenocarcinoma (PDAC), where protumoral IL-1beta+ TAMs were found to originate from monocytes but not from FOLR2+ resident macrophages." (PMID 39516356, 2024). "However, the co-localization of fetal-like FOLR2+ TAMs with Tregs and fetal-like ECs adjoining ALB+ tumor epithelial cells in HCC suggests that they do not orchestrate an immunosuppressive TME alone." (PMID 36938978, 2023).
cancer (59 papers, 2011 to 2025). A tumor composed of atypical neoplastic, often pleomorphic cells that invade other tissues. "In this regard, the macrophage-specific Folate Receptor β (FRβ, encoded by the FOLR2 gene) has been already validated as a target for molecular delivery in cancer as well as in macrophage-targeting therapeutic strategies for chronic inflammatory pathologies." (PMID 32532019, 2020). "Indeed, we show that the inflammatory signature of CXCL-iFibro is functionally relevant, as CXCL-iFibro are able to attract CD14+ monocytes and to polarize them into FOLR2+ macrophages, which have been recently described in cancer and diabetic kidney." (PMID 38272907, 2024). "Folate receptor (FR) alpha (FOLR1) and beta (FOLR2) are membrane-anchored folate transporters that are expressed at low levels in normal tissues, while their expression is strongly increased in several cancers." (PMID 38212621, 2024). "Studies have shown that FOLR2 expression accounts for the maturation and enrichment of macrophages, and that FOLR2+ macrophages may be involved in regulating cancer progression, immune response, and angiogenesis." (PMID 38068740, 2023). "Therefore, targeting FOLR2 in TAM could be a potential treatment for cancer patients." (PMID 37351109, 2023). "Indeed, we identify several populations of macrophages in CKD, including FOLR2+ and TREM2+ macrophages, two TAM subsets recently discovered in cancer and still poorly described in kidney." (PMID 38272907, 2024).
infection (5 papers, 2019 to 2025). The state of being infected such as from the introduction of a foreign agent such as serum, vaccine, antigenic substance or organism. "It is possible that there was an increased translation of exiting transcripts of FOLR2 or the regulation of translation, resulting in the persistent overexpression of the protein even at 6 h post-Bb infection." (PMID 31316336, 2019). "Throughout the whole infection course in our study, the expression changes of FOLR2 were the most significant among all the DEGs which inevitably attracted our attention." (PMID 31316336, 2019). "We investigated whether an anti-folate receptor beta mAb that can promote clearance of activated macrophages during chronic disease could reduce inflammation during CCHFV IbAr10200 infection." (PMID 39513496, 2024). "However, the protein expression of FOLR2 was upregulated at 6 h after Bb infection, which was inconsistent with the mRNA level, possibly due to the regulation of translation." (PMID 31316336, 2019). "In addition, we propose that FOLR2 is closely related to pathogenesis of Bb-induced infection in brain for the first time." (PMID 31316336, 2019). "In the intestine, coinfection resulted in the distinct upregulation of multiple inflammatory and stress-related gene signatures, including FOLR2 and PLA2G4F, which were not significantly upregulated in the single-infection cohorts." (PMID 41268552, 2025).
adenocarcinoma (2 papers, 2015 to 2020). A common cancer characterized by the presence of malignant glandular cells. "Similar to fallopian tube normal and adenocarcinoma samples, and in contract to normal ovary, EOC showed abundant expression of FOLR1 mRNA in the epithelial tumor cells whereas FOLR2 expression was restricted to stromal cells." (PMID 25971554, 2015). "Using RNAscope, a novel ISH method, we confirmed the similarities between EOC and fallopian tube, normal and adenocarcinoma using FOLR1, FOLR2, CD68 and CD11b markers." (PMID 25971554, 2015).
kidney disease (2 papers, 2021 to 2024). "Consistent with the accumulation of the CXCL-iFibro population at early stages of kidney disease, we show its probable function in the progression of the pathology by highlighting its reciprocal crosstalk with FOLR2+ macrophages." (PMID 38272907, 2024).
FOLR2 also shares sentences with these, for which no sentence is quoted: acute myeloid leukemia (8 papers); pulmonary fibrosis (7); autoimmune disease (5); colon adenocarcinoma (5); myelogenous leukemias (5); breast tumors (4); pancreatic cancer (4); leukemia (3); colon cancer (2); Crohn disease (2); idiopathic pulmonary fibrosis (2); liver cancer (2); lung squamous cell carcinoma (2); lymphoma (2); multiple sclerosis (2); psoriasis (2); thymoma (2); ulcerative colitis (2); viral infection (2); alopecia (1); anencephaly (1); atopic dermatitis (1); autoimmune (1); autoimmune myocarditis (1); blood cancers (1); brain cancer (1); chronic kidney disease (1); chronic myelogenous leukemia (1); chronic obstructive pulmonary disease (1); colitis (1).
A further 31 diseases each share a sentence with FOLR2 in 1 paper.